MIR587 (microRNA 587)
Synonyms: hsa-mir-587; MIRN587
Gene: MicroRNA gene on chromosome 6 (106,784,125 to 106,784,220, forward strand). Ensembl gene ENSG00000207577.
Homologues: Orthologues: chimpanzee ptr-mir-587 (100% identical).